EGFR (epidermal growth factor receptor)
Diseases named in the same sentence as EGFR in open-access papers (continued):
Sharing a sentence is not in itself a finding about the gene and the disease.
colon carcinoma (continued). "In addition, miR-147 dramatically reversed the intrinsic drug resistance associated with the “epithelial” EGFR inhibitor, gefitinib, in the colon cancer cell line HCT116." (PMID 24454732, 2014). "A recent study showed that colon cancer patients who underwent cetuximab therapy could acquire a new mutation in the ECD-domain of the EGFR gene that blocks binding of EGFR to cetuximab." (PMID 23990977, 2013). "However, in the present study, we showed that guggulsterone caused robust proliferation of two human colon cancer cell lines through Src-mediated activation of EGFR and post-EGFR signaling." (PMID 23119029, 2012). "Since DHA and EPA are both long chain omega-3 fatty acids that have been shown to reduce colon tumor development, we examined whether each of these fatty acids cause an increase in EGFR phosphorylation or if the effect is specific to DHA." (PMID 22761867, 2012). "Since KRAS analysis is now widely available due to its application as a predictive marker for anti-EGFR therapy in colon cancer, this diagnostic tool could also be applied to help the clinician in managing pancreatic masses." (PMID 24212643, 2011). "Since the expression of KRAS mutations hinder the use of anti-epidermal growth factor receptor (EGFR) treatments, the presence of CTCs harboring KRAS mutations in wild-type colon cancers might explain the therapeutic EGFR inhibition failure, thus being indicative of treatment resistance." (PMID 35582538, 2022). "Furthermore, it was demonstrated that HTyr significantly down-regulates epidermal growth factor receptor (EGFR) expression, which was associated with reduced cell proliferation of human colon cancer cells and decreased tumor growth and EGFR expression levels in HT-29 xenografts." (PMID 31137753, 2019). "Activation of the epidermal growth factor receptor (EGFR) plays a pivotal role in invasive processes in colon carcinoma cells and can also influence cell survival." (PMID 40761247, 2025). "Results:rTBL-1 exhibited cytotoxic effects in a concentration-dependent manner in both EGFR+ (MC-38) and EGFR− (CT-26) colon cancer cells with LC50 values of 23.50 and 30.01 μg/mL, respectively (p = 0.063)." (PMID 40006027, 2025). "Upon administering EGF to SLC5A1 knockdown colon cancer cells, the EGFR phosphorylation level was restored." (PMID 39781340, 2025). "Post hoc analyses of the PEAK and PRIME trials indicated that anti-EGFR therapy particularly benefits patients with left-sided colon tumors and RAS wild-type status." (PMID 40428735, 2025). "Our results indicate that colon cancer cells, both EGFR+ (MC-38) and EGFR− (CT-26), are responsive to 8 h in vitro treatment with rTBL-1, presenting LC50 values of 23.50 and 30.01 μg/mL, respectively (p = 0.063)." (PMID 40006027, 2025). "Subsequently, we demonstrated that rTBL-1 establishes supramolecular interactions matching at a significant level with EGFR on the surface of colon cancer cells, followed by lysosomal degradation of the receptor." (PMID 40006027, 2025). "Twenty-six (47.2%) patients with left-sided colon cancer and 3 (33%) patients with right-sided colon cancer used anti-EGFR, and all patients used anti-VEGF." (PMID 40587729, 2025). "Enhancing anti-EGFR efficacy of cetuximab by increasing ROS production in KRAS mutant colon cancer cell xenografts overexpressing SVCT2 (P < 0.05)." (PMID 40950984, 2025). "Previous studies have shown that tumor progression in metastatic colon cancer is associated with VEGF and EGFR (Epidermal Growth Factor Receptor) signaling, and that inhibitors targeting the VEGF family are used in colon cancer treatment." (PMID 41441010, 2025). "Raman imaging of tumour samples revealed an astonishing up-regulation of epidermal growth factor receptor (EGFR) on LS174T colon cancer cells." (PMID 41009762, 2025). "Detailed analyses reveal that the apoptotic process induced by rTBL-1 in colon cancer cells is slower and longer-lasting in MC-38 EGFR+ cells than in CT-26 EGFR− cells." (PMID 40006027, 2025).
colon carcinoma (continued). "Studies in colon cancer revealed that CHRM3 was able to facilitate ACh-induced EGFR signaling activation." (PMID 41516199, 2025). "In many types of cancer, i.e., lung, kidney, breast, head and neck, pancreas, bladder, and colon cancer, epidermal growth factor receptor (EGFR) appears to be expressed more than normal on the cell surface." (PMID 40332084, 2025). "In this context, ANXA1 facilitates EGFR activation and stabilization, supporting the development of new therapeutic targets in colon cancer and RC." (PMID 41283264, 2025). "This was in line with a previous study in which genistein decreased EGFR activation in HCT 116 colon cancer cells." (PMID 41354896, 2025). "Herein, we focused on colon cancer to figure out the remedial impacts related to the secretome of MSCs (as a new strategy) through EGFR/c-Src/IRSp53/p-AKT/p-Stat3/cyclin D1 signaling pathway." (PMID 41200137, 2025). "Since this is the first time that we have tested the bioactivity of rTLB-1 against murine colon cancer cells, as well as in an EGFR− tumor type, we set out to evaluate the level of apoptosis induced by the treatment." (PMID 40006027, 2025). "In previous studies, we have observed that the cytotoxicity induced by rTBL-1 in EGFR+ human colon cancer cells is related to apoptosis induction." (PMID 40006027, 2025). "In colon cancer, combinations of EGFR, BRAF inhibitors, chemotherapy, and immune therapy have been tested." (PMID 40977811, 2025). "It has been shown that simultaneous inhibition of the insulin receptors, IGF1 and MET receptors as well as the epidermal growth factor receptors (EGFR) enhances efficacy of EGFR-inhibitors in colon cancer xenografts." (PMID 40677714, 2025). "Studies have shown that rAj-HRP inhibits the ex vivo activity of human colon cancer HCT116 cells by acting on both the EGFR signaling and apoptosis pathways, targeting EGFR." (PMID 40003950, 2025). "Our results indicated IRSp53 upregulation in patients suffering colon cancer and reduction of EGFR/c-Src/IRSp53/p-AKT/p-Stat3/cyclin D1 signaling pathway, which led to suppression of cell proliferation in the hAMSCs-treated HT-29 colon cancerous cells." (PMID 41200137, 2025). "For example, in colon cancer, it has been observed that the clinical efficacy of combined EGFR/BRAF/MEK targeting correlated with increased ERK suppression." (PMID 41154654, 2025). "Our results indicate that the ability of rTBL-1 to induce apoptosis in colon cancer cells does not only depend on the availability of EGFR in the tumor cell, given the existence of unexplored mechanisms independent of this receptor." (PMID 40006027, 2025). "In colon cancer cell lines harboring BRAF V600E mutations, EGFR re-activates MAPK conferring resistance to BRAF inhibition with vemurafenib." (PMID 40869231, 2025). "After adding hesperidin and EGF to colon cancer cells, the EGFR phosphorylation levels were more increased than those of colon cancer cells treated solely with Hesperidin, while the protein level of EGFR remained unchanged." (PMID 39781340, 2025). "We identified a direct SLC5A1-EGFR interaction essential for regulating EGFR activity in colon cancer." (PMID 39781340, 2025). "Multiple studies suggest that the epidermal growth factor receptor (EGFR) pathway plays a role in colon cancer development." (PMID 38609520, 2024). "Cetuximab, a targeted therapy specifically designed for EGFR, has shown remarkable efficacy in treating colon cancer patients, resulting in improved prognosis and prolonged survival." (PMID 38326807, 2024). "Co-targeting of KRAS-MAPK and adaptive EGFR/HER1 signaling is a well-proven strategy in colon cancer." (PMID 38509064, 2024). "Combined BRAF, MEK, and EGFR inhibition can induce clinical responses in BRAF-V600E-mutant colon cancer, but rapid resistance often occurs." (PMID 39626159, 2024). "Enhanced CBL activity leads to the downregulation of EGFR expression and the inhibition of colon tumor cell proliferation." (PMID 39130630, 2024).
colon carcinoma (continued). "Targeted studies revealed that selected bile acids stimulate proliferation of colon cancer cells via activation and transactivation, respectively, of M3R and EGFR." (PMID 38791353, 2024). "Studies have indicated that c-Met and EGFR are overexpressed in 78–80% of colon cancers, correlating with poor outcomes." (PMID 39519855, 2024). "In this study, we established a link between HB-EGF and/or EGFR signaling and the action of the tumor-suppressor miR-126 and the oncogene miR-221 in colon tumor formation and growth using murine models of CAC and CRC." (PMID 39419989, 2024). "The extracellular domain of EpCAM stimulates proliferation of colon cancer cells, and this effect is inhibited by an EGFR inhibitor." (PMID 39594667, 2024). "Our results demonstrate that USP21 enhances EGFR expression by stabilizing the receptor through deubiquitination, thus promoting EGFR-mediated signaling in colon cancer cells." (PMID 39695128, 2024). "The potential activity of EGFR/HER2 inhibitor (lapatinib) combined with HDACi Panobinostat in colon cancer cells has been demonstrated, and further evaluation of the efficacy of this combination in the treatment of CRC is warranted." (PMID 39268463, 2024). "EGFR activation induced by the extracellular domain of EpCAM promotes cell migration of the colon cancer cells and this effect is abolished in cells treated with an EGFR inhibitor." (PMID 39594667, 2024). "For instance, in EGFR(+) colon cancer patients resistant to cetuximab, carfilzomib can enhance apoptotic signaling through ERS, serving as a viable alternative to cetuximab." (PMID 39080273, 2024). "For example, EGFR is active in both colon cancer and melanoma, but the comparatively higher levels of EGFR expression in colon cancer cause it to develop drug resistance significantly faster than in melanoma." (PMID 38539548, 2024). "About 40% of colon tumors have mutations in the KRAS proto-oncogene, which are associated with resistance to biological therapy, i.e., monoclonal antibodies directed against epidermal growth factor receptor (anti-EGFR ab)." (PMID 39202071, 2024). "EGFR alterations have been described in several other malignancies such as colon cancer and non-small-cell lung cancer (NSCLC)." (PMID 39273661, 2024). "Further studies are needed to gain a deeper understanding of the molecular interactions related to the lectin’s cytotoxic effects to develop new strategies against EGFR-dependent cancers, particularly colon cancer." (PMID 39769023, 2024). "Tephrosin has been reported to have anticancer effects by inducing the degradation and internalization of the EGFR in human colon cancer cells, suggesting that tephrosin possibly restored paclitaxel sensitivity by inhibiting the EGFR signaling pathway." (PMID 38137377, 2023). "As shown, the sialylation of the EGFR affects EGFR-mediated cell growth and reduces sensitivity to gefitinib in human colon cancer cells, whereas the anticancer effect of gefitinib was augmented in ST6Gal-1-deficient cells." (PMID 37894470, 2023). "More specifically, when Sia acetyl modifying protein, CASD1, is knocked out via CRISPR Cas9 genome editing, lung and colon cancer cells tend to upregulate their activated EGFR expression levels to compensate for the genetic aberration." (PMID 37687086, 2023). "Lauric acid was found to downregulate the EGFR signaling pathway in colon cancer cells to impart cell death." (PMID 37835375, 2023). "Overall, the data suggest that atropine exhibits its effect by inhibiting EGFR and pERK in human colon cancer cell lines." (PMID 37828429, 2023). "This ADAM17/EGFR/miR-145 feedback loop contributes to the migration and invasion of cancers such as nasopharyngeal cancer, colon cancer, hepatocellular cancer, renal cancer, and so on." (PMID 37521117, 2023).
colon carcinoma (continued). "Extracellular galectin-3 interacts with the EGFR and increases EGFR phosphorylation and activation, resulting in colon cancer cell migration." (PMID 36823664, 2023). "The resected specimen of the colon cancer had wild-type KRAS mutation, indicating that the patient was a candidate for anti-EGFR therapy." (PMID 37872388, 2023). "The receptor tyrosine kinase pathway, particularly the EGFR pathway, can cross-regulate Wnt signalling in colon cancer." (PMID 38137047, 2023). "In the present study, we report that ST6GAL1-mediated sialylation activates EGFR in seven different cancer cell models including ovarian, pancreatic, and colon cancer cells." (PMID 37660914, 2023). "SW-480 colon cancer cells exhibited high EGFR expression and have shown sensitivity to the apoptotic effect of TBLF." (PMID 37259433, 2023). "To confirm PKC and EGFR activation play a role in MR agonist-induced binding of βPix to β-catenin, we treated HT-29 colon cancer cells with phorbol 12-myristate, 13-acetate (PMA), a selective PKC activator and epidermal growth factor (EGF)." (PMID 37805544, 2023). "A significant predictor of the success of anti-epidermal growth factor receptor (EGFR) therapy in people with metastatic RAS wild-type colon cancer is sidedness." (PMID 36819360, 2023). "For instance, cetuximab conjugated nanoparticles were developed to actively target epidermal growth factor receptor (EGFR) overexpressing colon cancer cells." (PMID 37190185, 2023). "Clinical data show that the expression of EGFR in colonic mucosa is increased in both UC and colon cancer patients." (PMID 38196993, 2023). "Fisetin stimulates epidermal growth factor receptor/NF-κB -mediated apoptosis in cyclooxygenase COX-2 overexpressed human colon cancer cell line HT29." (PMID 37565061, 2023). "Our results show that rTBL-1 affects human colon cancer cells by affecting EGFR pathways, mostly by partially degrading the receptor and activating p38 MAPK signaling." (PMID 37259433, 2023). "A significantly higher number of male patients were diagnosed with colon cancer (n = 69; 62.2%), and 73 patients (male and female combined) were treated with first-line anti-EGFR medication (65.8%)." (PMID 36980549, 2023). "EGFR is overexpressed in 60% to 80% of colon cancers, leading to development of EGFR-targeted drugs, an important tool for treating cancer." (PMID 37853459, 2023). "EGFR signaling plays an important role in colon cancer progression therefore, the EGFR pathway is an important inhibitor of tumor growth." (PMID 36807774, 2023). "A positive correlation was found between linc-ROR and epidermal growth factor receptor (EGFR) signaling in colon cancer, in which linc-ROR served as a tumor-promoting factor via repressing the ubiquitination and degradation of EGFR signaling." (PMID 36827545, 2023). "Compared with the wild-type colon cancer cells, the G13D mutation on KRAS determines a reduction in the responsiveness of LoVo cells to cetuximab and panitumumab, drugs that target the epidermal growth factor receptor (EGFR)." (PMID 38139304, 2023). "Genistein derivatives have been shown to inhibit phosphorylation of Epidermal Growth Factor Receptor (EGFR) at two tyrosine sites in a concentration-dependent manner after 24h of treatment in two colon cancer cell lines." (PMID 36905879, 2023). "Various medicines targeting EGFR have been developed and approved for several cancer types, such as lung and colon cancer." (PMID 37623233, 2023). "Pancreatic, ovarian, and colon cancers have been associated with VEGF, EGFR, SRC, and JAK overexpression and STAT3 activation." (PMID 36852795, 2023).
colon carcinoma (continued). "A study on colon cancer also showed that phosphorylation of the EGFR and downstream signal activation is enhanced by DSG2, where downregulation of DSG2 decreases EGF-induced cell proliferation and suppresses in vivo xenograft tumor growth." (PMID 38188287, 2023). "To investigate the effects of ST6GAL1-mediated sialylation on EGFR activity, we assessed EGFR activation in pancreatic, ovarian, and colon cancer cell lines in which ST6GAL1 expression was directly modulated." (PMID 37660914, 2023). "Anti-EGFR therapy has been known to be less effective for right-sided colon cancer than for left-sided colon cancer." (PMID 37872388, 2023). "Some studies have demonstrated that the K-ras mutant type of colon cancer cell releases exosomes that carry mutant K-ras and various growth-promoting proteins such as EGFR, Src family kinases, and integrins." (PMID 37373600, 2023). "Genetic background profoundly affects the robustness of EGFR inhibition in preclinical CRC models, as most colon tumors are EGFR dependent in B6J mice while being EGFR independent in humans, providing evidence for the observed lack of translation." (PMID 37712424, 2023). "As well, compared with patients with colon cancer, those with rectal cancer had significantly lower odds of receiving EGFR or VEGF inhibitor therapy (aOR, 0.59; 95% CI, 0.50-0.68)." (PMID 36656585, 2023). "To visualize EGFR molecules in live cancer cells, we generated a human colon carcinoma cell line stably expressing EGFR–GFP." (PMID 35612280, 2022). "EGFR is naturally overexpressed in the vast majority of colon cancers, and it is already targeted in CRC with two FDA-approved antibodies, including Cetuximab." (PMID 35177811, 2022). "Like in other cancer cells, the activation of M3 in colon cancer cells induces transactivation of EGFR." (PMID 35565451, 2022). "Because epidermal growth factor receptor (EGFR) is a critical target for colon cancer therapy, the change in EGFR expression under Formula X treatment was also examined." (PMID 35721174, 2022). "The EGFR expression in the human colon tumor cell line HT29 and the human stomach tumor cell line MGC803 were verified using western blotting and immunocytochemistry." (PMID 35903247, 2022). "For instance, the EGFR/PI3K/AKT/mTOR axis plays an important role in promoting TAM M2 polarization by secreting EGF from colon cancer cells." (PMID 36466812, 2022). "In this study, we used the self-assembly method to investigate the effect of CPT-11-loaded DSPE-PEG2000 targeting EGFR liposome on the SW620 colon cancer cells." (PMID 35918704, 2022). "Here, intracellular ROS was measured in human colon cancer cells SW620 treated with CPT-11-loaded-liposome or free CPT-11 or CPT-11-loaded EGFR-targeted DSPE-PEG2000 liposome (EGFR-Lipo-CPT-11)." (PMID 35918704, 2022). "The highest mean fluorescence intensity (MFI) displayed by the EGFR-Lipo-CPT-11 group precisely confirmed that EGFR-Lipo-CPT-11 treatment strongly enhanced the ROS production SW620 colon cancer cell lines, besides similar results with the cell viability test." (PMID 35918704, 2022). "Another study demonstrated that phosphorylation of EGFR at serine 1046/1047 via activation of p38 mitogen-activated protein kinases played a pivotal role in EGCG-induced downregulation of EGFR in colon cancer cells." (PMID 35893779, 2022). "The activation of EGFR by ACh and bile acids in colon cancer cells was studied, confirming the activation of M3 in proliferation via MAPK (ERK1/2)." (PMID 35565451, 2022). "It is worth noting that EGFR has been proven to have good success as a drug-targeted therapy for colon cancer and has been used in clinical settings." (PMID 36258178, 2022). "As with the RAS mutation, an intrinsic resistance to drugs causes inhibition higher up the pathway, which is the case for the anti-EGFR monoclonal antibodies used in colon cancer treatments such as cetuximab, panitumumab, and bevacizumab." (PMID 36005935, 2022).